MMP9 (matrix metallopeptidase 9)
Diseases named in the same sentence as MMP9 in open-access papers (continued):
Sharing a sentence is not in itself a finding about the gene and the disease.
tumor (continued). "Studies have shown LDHC promotes tumor cell invasion and migration by inducing epithelial-mesenchymal transition and the expression of matrix metalloproteinase-9 (MMP9), and this leads to a poor prognosis for tumor patients." (PMID 34852326, 2021). "MMP-9 is particularly correlated with pro-oncogenic events such as neo-angiogenesis, tumor cell proliferation, and metastasis." (PMID 34771620, 2021). "MMP9 and E-cadherin are involved in tumor invasion and metastasis, while Ki67 is a well-known proliferation marker for the evaluation of cell proliferation." (PMID 34376192, 2021). "It has been demonstrated that NE or MMP-9 in NETs can promote tumor growth and migration by degrading ECM." (PMID 34327245, 2021). "Myeloid-derived suppressor cells (MDSCs) secrete MMP9 which drive tumor cell invasion and metastasis." (PMID 34220337, 2021). "It is known that MMP-7 and MMP-9 are also strong promoters of cancer progression and metastasis of malignant tumor cells." (PMID 33435313, 2021). "While ECM degradation is considered a key step promoting tumor progression, MMPs family, especially MMP9 plays a significant role in this process." (PMID 34239873, 2021). "In this context, MMP-9 derived from tumor cells, including NSCLC and neutrophils, promotes proteolytic activation of latent TGF-β1 in the TME, resulting in immunosuppression and tumor progression." (PMID 34168563, 2021). "The next step was the determination of the potential downstream effector, which links loading-driven regulation of the dopamine-Lrp5 axis to tumor-promoting genes such as Snail, MMP9, and Runx2." (PMID 34031366, 2021). "Hsp90ab1 reduced the scratch-based migration and downregulated tumor-promoting genes Lrp5, MMP9, Runx2 and Snail in 4T1.2 cells." (PMID 33859739, 2021). "Several studies indicate that an overexpression of MMPs such as MMP-9 is highly correlated with tumor progression including invasion, angiogenesis and metastasis in pancreatic cancer." (PMID 33730072, 2021). "The metalloproteinase MMP-9 is involved in remodeling of the extracellular matrix to mediate tumor cell migration and invasion." (PMID 34903245, 2021). "Most of the miR-224-associated studies have been conducted in human cancer cells, with miR-224 reported to promote the expression of tumor invasion-associated proteins p-PAK4 and MMP-9 by directly targeting HOXD10." (PMID 34379706, 2021). "The proinvasive MMP-9 is also observed in large blood vessels and surrounding tumor cells, with intense immunofluorescence in UII-treated xenografts." (PMID 33937253, 2021). "In NB, however, MMP-9 has only been shown to be present in the tumor-surrounding stroma, consisting of fibroblasts and (peri-)vascular cells, but not specifically to be derived from MSCs." (PMID 33287630, 2021). "MMP9 produced by neutrophils promotes the angiogenic switch by inducing VEGF expression in the tumor and we observed an up−regulation of VEGFR signaling." (PMID 34070438, 2021). "Of these OPN, IL-33, CCL17, and MMP-9 were significantly reduced in the lung of 4T1 tumor-bearing mice treated with WECS." (PMID 34771120, 2021). "Western blotting of nude mouse tumor tissues showed that TPL not only inhibited tumor growth, but also reduced the expression of MMP9, MMP2, VEGF, p-PI3K, p-AKT, and p-p65 protein." (PMID 34381726, 2021). "Many previous studies have demonstrated that Mmp-2 and Mmp-9 are closely related to tumor invasion and metastasis." (PMID 34539418, 2021). "The protein concentrations of MMP-1, MMP-2, MMP-3, and MMP-9 also have been seen to be greater in OSCC tumor tissue in contrast to control tissue." (PMID 33892690, 2021). "Our results demonstrate that zinc phthalocyanine (ZnPc)-PDT with 12 J/cm2 or 24 J/cm2 irradiation can substantially decrease tumor migration via downregulating MMP9 and ROCK1 and inhibit the clonogenicity of SW480 cells via downregulating CD44 and SOX2." (PMID 34833970, 2021).
tumor (continued). "Before examining potential tumor suppressors, we found that the levels of IL1β, Runx2, MMP9, TGFβ, and Snail in EO771 cells were downregulated by osteocyte-derived CM, and their levels were further reduced by the overexpression of the three selected genes." (PMID 33802279, 2021). "In various human cancers, MMP9 is an important target and biomarker for tumor invasion, metastasis, and angiogenesis." (PMID 33799999, 2021). "It was also shown that infiltrating neutrophils promote angiogenesis in the tumor microenvironment acting as a primary source of MMP-9." (PMID 34200529, 2021). "The expression of MMP-2 and MMP-9 in the cancer tissues is enhanced with the increase of tumor pathological stage (MMP-2: F = 3.884, p = 0.029, MMP-9: F = 3.783, p = 0.032)." (PMID 31882379, 2021). "Different studies have now suggested a key role for MMP9 in development of a proper microenvironment for promotion of tumor growth and angiogenesis by enhancing the interrelation between VEGF and VEGFR2." (PMID 34344421, 2021). "Ki-67, MMP-9, and vimentin are commonly used to evaluate the proliferative and invasive capacities of tumor cells, respectively, where increased expression indicates a higher capacity." (PMID 34635636, 2021). "MMP-2 and MMP-9 are zinc-dependent ECM degrading enzymes involved in the metastatic activity of tumor cells." (PMID 34400947, 2021). "MMP2 and MMP9, also known as Gelatinase A and B, play key roles in the carcinogenesis of BC, with functions in cell proliferation, inflammation, angiogenesis, tumor invasion and metastasis." (PMID 33568081, 2021). "MMP9 also correlated with the locally advanced stage of tumor (χ2 = 7.09, P = 0.008) with higher MMP9 expression seen in 84.4% of all locally advanced tumors." (PMID 33420101, 2021). "This study's western blot results showed that the recombinant Hespintor group and the Sorafenib group displayed significantly inhibited expressions of MMP2 and MMP9 in the nude mice's tumor tissues." (PMID 33391431, 2021). "MMP-2 and MMP-9 promote the degradation of basement membrane and lead to tumor cell invasion and metastasis." (PMID 35002708, 2021). "In the Huh7/H22 tumor model, the expression of N-cadherin, Snail, Twist, and MMP9 was significantly decreased after CPT administration (CPT group and combined group), compared with the control group." (PMID 34178646, 2021). "Inhibition of MMP-9 activity by specific drugs or antisense oligonucleotide techniques impairs tumor progression and invasion." (PMID 34769032, 2021). "Here, we showed that the enzymatic activities of MMP2 and MMP9 were very low in normal tissues, while higher levels of both pro- and active forms were detected in the paired tumor samples of 24 patients." (PMID 34830271, 2021). "In the correlation analysis of tumor immune cell infiltration, MMP9 was positively correlated with M0 macrophages and resting NK cells and negatively correlated with activated mast cells, resting mast cells, monocytes and activated NK cells." (PMID 35201491, 2021). "MMP-9 levels are substantially lower in CXCR4-deficient cells, and CXCR4 down-regulation reduces tumor development in vivo." (PMID 33946372, 2021). "Especially, increased expression and activity of MMP-2 and MMP-9 subtypes in tumors are known to be related to the degradation of basement membranes—an essential step in tumor invasion and in enhancing angiogenesis." (PMID 33498762, 2021). "CXCL12 recruits CXCR4+ BMDCs to the tumour, including vascular progenitor cells that can differentiate and incorporate into new blood vessels, but also MMP-9-expressing myeloid cells that indirectly regulate tumour angiogenesis." (PMID 33803414, 2021). "Among MMPs, MMP-2 and MMP-9 are receiving renewed interest as validated druggable targets for halting different tumor progression events." (PMID 34638665, 2021). "MMP9 is a specific member of this group and its expression by tumor epithelia regulates inflammation, ECM remodeling, and neovascularization." (PMID 34503132, 2021).
tumor (continued). "The Lrp5-dependent mechanism was evident since Lrp5-overexpressing osteocytes inhibited the growth of tumor spheroids and Lrp5-silenced osteocytes upregulated tumorigenic genes such as Runx2, MMP9, Snail, and TGFβ." (PMID 33450808, 2021). "Compared with TIE2− TAMs, TIE2+ TAMs within the same tumor express higher levels of pro-angiogenic genes, including MMP9, VEGFA, COX2, WNT5A, and PDGFB." (PMID 34603327, 2021). "Lidocaine blocked tumor cells invasion and MMP-9 and FAK secretion by attenuating Src-dependent inflammatory signaling pathways." (PMID 34249706, 2021). "Among MMP types, MMP2 and MMP9 promote the invasion and metastasis of tumor cells by degrading type IV collagen, a main component of the ECM." (PMID 33747258, 2021). "Administration of miR-1293 antagomir reduced tumor volume and staining of Ki-67 and MMP9, but elevated PGM5 expression in vivo." (PMID 34616611, 2021). "The co-culturing of tumor spheroids with Lrp5-overexpressing osteocyte spheroids shrank tumor spheroids, and their CM downregulated MMP9, Runx2, TGFβ, and Snail." (PMID 33450808, 2021). "It has been reported that MMP-2 and MMP-9 are extracellular proteolytic enzymes that play an important role in tumor invasion." (PMID 33737656, 2021). "MMP9 expression was reported to increase with tumor size and be significantly higher in metastatic NSCLC cases than in cases without metastasis." (PMID 34209215, 2021). "Neutrophils produce and release mediators that promote angiogenesis (e.g., VEGF, MMP-9, and Oncostatin M), modulate the microarchitecture of tumor tissues by releasing proteases, accelerate tumor cell proliferation, and induce genetic instability." (PMID 34072260, 2021). "To further investigate the underlying mechanism, we evaluated the expression of RhoC, Src, and F-actin (the key regulators of tumor cell metastasis) in the MMP-9/shRNA-transfected OSCC cells by real-time PCR, western blotting, and IHC." (PMID 33828938, 2021). "KDM1A can apparently inhibit the expression of TIMP1 by demethylating H3K4ME2 in the TIMP1 promoter region, activating MMP9, which is responsible for tumor migration and PTC invasion through this pathway." (PMID 34055497, 2021). "The diminished angiogenic response was also seen in tumours established from Mmp-9 knockout cells or tumours treated with CXCR4 inhibitor AMD3100." (PMID 33803414, 2021). "MMP9 functions predominantly as a collagenase to promote tumor invasion and metastasis by degrading type IV collagen, a major component of basement membrane and the ECM." (PMID 34239873, 2021). "It is essential for tumor growth and progression, therefore, MMP-9 expression is significantly higher among PTC patients with larger tumor size, especially in tumors >2 cm." (PMID 34684168, 2021). "MMP9 plays a crucial role in ICC invasion and metastasis, and its association with Gal-3 in tumor progression has been previously stated." (PMID 34109213, 2021). "In vivo, tumor angiogenesis is strongly inhibited in MMP-9 KO mice or by chemical compounds inhibiting MMP-9." (PMID 33783686, 2021). "M2 type macrophages closely resemble tumor-associated macrophages (TAMs) and are characterized by increased expression of IFN-γ, CCL2, CCL5, CXCL16, CXCL10, CXCL9, TNF-α, MMP9 and IL-10, arginase-1, and peroxisome proliferator-activated receptor-γ (PPAR-γ)." (PMID 33925575, 2021). "In the present study, the mRNA and protein expression of MMP-9 was strengthened with the increase of tumor pathological stage." (PMID 31882379, 2021). "MMP9 staining showed the expression on the tumor cells of VSCC and SCC, especially in the periphery of the tumor nest." (PMID 35008304, 2021). "The matrix metalloprotease-9 (MMP-9) in tumor tissues was significantly lower in mice treated with Avastin alone than in controls and were further lower in those treated with Avastin plus the FO/Se supplements." (PMID 33805447, 2021).
tumor (continued). "The expression levels of MMP2, MMP9, Bax, Bcl-2, and caspase-3 in the tumor organizations were detected with Western blot." (PMID 33391431, 2021). "MMP9 is a matricellular protein associated with extracellular matrix (ECM) remodelling, promoting tumour progression, and modulating the activity of cell adhesion molecules and cytokines." (PMID 34777466, 2021). "MMP-9 can inactivate or antagonize the biological functions of tumor-suppressing cytokines and chemokines by proteolytic cleavage and thereby jeopardize the efficacy of chemoimmunotherapy." (PMID 34959271, 2021). "The majority of studies revealed a positive correlation between MMP-9 expression and advanced tumor stage." (PMID 34684168, 2021). "The mesenchymal components including MMP-2 and MMP-9 can contribute to tumor invasion through breaking down of basement membrane including Coll-IV." (PMID 33937253, 2021). "Secretion of MMP-9 is low in resting cells, but increases significantly during tissue remodeling following wound healing or tumor invasion, and is thought to promote metastasis." (PMID 33807594, 2021). "Increased expression of MMP-2 and MMP-9 was reported to induce tumor angiogenesis, inflammation, and cancer metastasis." (PMID 33926142, 2021). "In response to the loading-driven elevation of dopamine, we evaluated the expression of Lrp5 and downstream effector genes in tumor cells, including tumor-promoting cytokines and oncogenic genes such as Src, Snail, MMP9, Runx2, and TGFβ." (PMID 34031366, 2021). "MMP-9 enhances metastasis of tumor cells by degrading collagen proteins of the ECM after being activated by extracellular proteases under different physiological and pathological conditions." (PMID 31882379, 2021). "The role of MMP9 in the degradation of ECM and the basement membrane, NGAL and the MMP9/NGAL complex is thought to contribute to tumor progression, invasion, and metastasis." (PMID 33670492, 2021). "By regulating MMP9, it can interfere with the activities of the tumor microenvironment, thereby inhibiting the metastasis of cancer cells." (PMID 35069702, 2021). "MMP-9 is important for invasion, metastasis, and tumor angiogenesis, and its expression is known to be upregulated in several cancer cells, including HCC." (PMID 34069882, 2021). "Among all the MMP proteins identified so far, MMP-2 and MMP-9 are considered to be the most crucial members involved in tumor migration and invasion." (PMID 34149918, 2021). "It is well established that epithelial-to-mesenchymal transition (EMT) and matrix metalloproteinases (MMPs; e.g. MMP9) play crucial roles in mediating tumor migration and invasion." (PMID 34149934, 2021). "The GEO cohort found that the expression of MMP9 was significantly up-regulated in tumor tissues (P=0.00016)." (PMID 33656546, 2021). "Differential expression analysis of the TCGA database showed that among the six characteristic IRGs, the MMP9 gene was significantly expressed in tumor tissues compared with adjacent normal tissues." (PMID 34671598, 2021). "In turn, MMP-9 is involved in the extracellular matrix degradation, and thus plays a crucial role in the angiogenesis and tumour progression." (PMID 34302052, 2021). "MMPs in cancer promote tumor angiogenesis, especially MMP9, which regulates the release and activation of vascular endothelial growth factor (VEGF)." (PMID 34572485, 2021). "Among these MMPs, MMP2 and MMP9 can selectively degrade type IV collagen, promoting tumor cells migrating through the basement membrane." (PMID 34820358, 2021). "A recent study suggested that MMP-9 protein was highly expressed in tumor tissues in vivo and played a crucial role in the degradation of the surrounding ECM and regulation of cell invasion in PDAC cells." (PMID 33730072, 2021). "The study also showed important differences in the levels of mRNA and protein overexpression of MMP-1, MMP-3 and MMP-9 in the tumor tissue compared to normal skin." (PMID 34204372, 2021).
tumor (continued). "This study proved that high expression of MMP9 existed in BRCA patients, along with a bad prognosis, and there was a close relationship between the expression level of MMP9 and the pathological stage of the tumor." (PMID 35069702, 2021). "MMP-9 is a tumor-derived matrix metalloproteinase that has a key role in tumor progression, metastasis, and tumor-induced angiogenesis." (PMID 33630973, 2021). "BPs were shown to reduce CD11b+ tumor-associated macrophages (TAMs), decreasing vascular endothelial growth factor (VEGF) and MMP-9 in the tumor microenvironment and leading to anti-angiogenesis." (PMID 34440747, 2021). "MMP-9, as a Matrix metalloproteinase, can destroy the integrity of the basement membrane and extracellular matrix and promote the detachment of tumor cells from the endothelium, which will lead to metastatic process." (PMID 34901004, 2021). "E-cadherin (E-cad) and matrix metalloprotein 9 (MMP9) are proteins necessary for tumor invasion and metastasis." (PMID 33257506, 2021). "For instance, IPA gene analyses revealed matrix metallopeptidase 9 (MMP9) as the most downregulated gene in the neoplasia stage." (PMID 34069906, 2021). "MMP-9 expression is correlated with age, sex, tumor size, site, histological types, lymphovascular invasion, tumor differentiation, depth of invasion (T), lymph node (N) metastasis, distant metastasis, and TNM stage." (PMID 34707964, 2021). "In cases with high MMP9 IHC scores, the volume of cytoplasmic positivity in tumor cells tended to become larger and the contours were more irregular." (PMID 33799999, 2021). "Mice in this group showed similar tumor sizes and weights, and according expression level of epithelial–mesenchymal transition molecules, including vimentin, MMP9, MMP2, AXIN-1, N-cadherin, and E-cadherin, compared to mice in the control group." (PMID 33608495, 2021). "Generally, increased expression of MMP-1, MMP-2, MMP-3, MMP-7, MMP-9, MMP-13, and MMP-14 are associated with cancer advancement, which relates to poor cell differentiation, tumor invasion, distant metastasis, and poor prognosis." (PMID 33892690, 2021). "Another pathway is the downregulation of MMP-7 and MMP-9, which are responsible for cancer progression and metastasis of malignant tumor cells." (PMID 33435313, 2021). "This gives TIMELESS a new role in the field of the tumor and provides a basis for further revealing the fine regulatory mechanism of MMP9." (PMID 33430865, 2021). "Specifically, MMP2 and MMP9 are considered to be critical in tumor metastasis because of their influences on ECM degradation and tissue remodeling." (PMID 33430855, 2021). "Tumor-associated neutrophils are able to release CXCR4, VEGF and MMP-9 to promote tumor bone metastasis." (PMID 34831167, 2021). "These cells showed increased expression of genes related to tumor growth (Cox2 and Vegfa), metastasis (Cox2, Mmp2, and Mmp9), and immune suppression (Ido2), indicating that TAM generation in vitro had been successful." (PMID 34900687, 2021). "Tumor-associated neutrophil cells (TAN) play an significant role in promoting angiogenesis, and they can affect tumor migration through releasing matrix metalloproteinase 9 (MMP9)." (PMID 34926571, 2021). "IL-2/α-CD40 combination therapy has enough potential to induce the IFN-α– and NO-dependent reduction of MMP9 expression in the tumor microenvironment and diminishes the probability of metastasis development to the lung." (PMID 32902664, 2021). "DLL4-Notch signaling pathway interacts with several molecules and other signaling pathways, including PI3k, EGFR, and MMP9, all related to tumor invasion, proliferation, and metastasis." (PMID 36643842, 2021). "MMP-9, similar to IL-6, is produced by various tumor cells and inflammatory cells—neutrophils, eosinophils, monocytes, lymphocytes, and alveolar macrophages." (PMID 34439874, 2021). "In this paper, we want to highlight a particular isoform of MMP-9, as a biomarker of progression from neoplasm to metastasis." (PMID 35723387, 2021).